BRCA1 (BRCA1 DNA repair associated)
Diseases named in the same sentence as BRCA1 in open-access papers (continued):
Sharing a sentence is not in itself a finding about the gene and the disease.
tumor (continued). "It has been observed that LMO2-positive tumor cells were sensitive to PARPi in various hematologic malignancies, different from solid tumors in which BRCA1/2 deficiency conferred synthetic lethality to PARPi." (PMID 37442994, 2023). "BC development in carriers of BRCA1/2 pathogenic variants usually involves somatic inactivation of the remaining BRCA1/2 allele in the tumor tissue." (PMID 36768191, 2023). "In total, an HRD was present in 44.7% (73/163) of the patients based on a GIS ≥ 42 in 42.9% of the patients and based on a tumor BRCA1/2 mutation in 3 cases (all with a GIS < 42)." (PMID 36765776, 2023). "This intervention induces DNA damage and synthetic lethality in tumor cells harboring BRCA1 or BRCA2 mutations." (PMID 37762577, 2023). "The only two BRCA1/2 pathogenic variants detected in patients diagnosed at ≥80 years old were small sequencing variants that were detected in tumour DNA (BRCA1:c.68_69del and BRCA2:c.4478_4481del)." (PMID 38201604, 2023). "BRCA1 methylation was enriched on the same allele in the tumor tissue and WBC in five of these individuals, indicating a shared clonal origin of the methylated normal and tumor cells." (PMID 38053165, 2023). "Nonetheless, CtipT855A/T855A cells did appear to retain some HDR activity, especially when compared to ES cells bearing a pathogenic mutation in the Brca1 tumor suppressor (Brca1S1598F/S1598F)." (PMID 38067190, 2023). "Breast Cancer 1 protein (BRCA1) is a tumor suppressor that is associated with repairing damaged DNA in double-stranded DNA breaks (DSBs)." (PMID 37509303, 2023). "Another hallmark of human BRCA1-mutated BLBC is the high frequency of copy number variations (CNVs) for genomic loci containing oncogenes or tumor suppressors." (PMID 37815460, 2023). "This patient also revealed a similar allele specific BRCA1 methylation in tumor and WBC samples (blue dot)." (PMID 38053165, 2023). "The concordance between germline BRCA1/2 pathogenic variants detected in germline and tumour DNA was 94% (44/47) and 100% (28/28) using our in-house tumour BRCA1/2 assay and Myriad’s myChoice® CDx, respectively." (PMID 36765687, 2023). "As classical tumor suppressors, BRCA1/2 mutations that are disease-associated are predominantly loss-of-function, with 70% of BRCA1 mutations leading to a loss of full-length protein." (PMID 37108225, 2023). "For example, deleterious genetic mutations in BRCA1, a tumor suppressor gene, can impair protein function and raise the risk of multiple cancers 1-3." (PMID 36593954, 2023). "For example, the efficacy of PARP inhibitors in tumours with germline BRCA1 or BRCA2 mutations has been well established, in both metastatic and early disease settings in breast and ovarian cancer." (PMID 37491606, 2023). "The overall concordance of germline BRCA1/2 pathogenic variants detected in germline and tumour DNA was clinically acceptable at 91.7% (33/36)." (PMID 38201604, 2023). "P/LP variants identified in tumor-only sequencing of GISTs were almost exclusively germline in certain genes, such as BRCA1, BRCA2 (4/4 variants), and SDHB (10/11 variants)." (PMID 36593350, 2023). "Functioning of all alternative pathways rely on PARP1 and PARP2 enzymes and inhibition of PARP1/2 enzymes in BRCA1/2-deficient tumor cells results in cell death." (PMID 37945748, 2023).
tumor (continued). "No pair-wise alterations were observed in BRCA1; one primary tumor (P2) and one recurrent tumor (R7) harbored a frameshift deletion and multiple BRCA1 mutations, respectively." (PMID 37761830, 2023). "BC genomes from CHEK2 mutation carriers were most similar to ER+ BC genomes and least similar to those of BRCA1/2 mutation carriers in terms of tumor mutational burden as well as mutational signatures." (PMID 37161532, 2023). "Olaparib and combination therapies similarly improved the median survival of Brca1- and Brca2-deficient tumour-bearing mice." (PMID 38017453, 2023). "The concordance of germline BRCA1/2 pathogenic variants in germline and tumour DNA was 91.7% (33/36)." (PMID 38201604, 2023). "Here, 97% of patients have ≥1 BRCA1/2 mutation with 95% concordance between germline and tumor mutations." (PMID 37803017, 2023). "The myChoice® CDx was able to detect most germline BRCA1/2 pathogenic variants in tumour DNA, although a proportion of pathogenic large rearrangements were not reported." (PMID 38201604, 2023). "ART899 is a deuterated form of ART812, the ART558 derivate shown to have efficacy in BRCA1/SHLD2-deficient tumor xenograft studies." (PMID 36689546, 2023). "Clustering based on these signatures supported that BRCA1/BRCA2-mutated tumours are clearly separated from non-BRCA1/BRCA2 tumours." (PMID 37316882, 2023). "Consensus was reached to trigger cascade germline genetic testing in metastatic PCa patients having BRCA1/2 tumour pathogenic variants." (PMID 36874601, 2023). "Women with EOC have a higher chance to benefit from platinum-based chemotherapy and PARP inhibitor therapy if their tumor has a germline or somatic BRCA1/2 pathogenic variant." (PMID 36922847, 2023). "BRCA1 (RNF53) is a tumor suppressor, which encodes a protein with E3 ubiquitin-protein ligase activity." (PMID 37304241, 2023). "Preclinically, PARP inhibition elicits a potent anti-tumour immune response through activation of the STING pathway in both BRCA1-deficient tumour cells and dendritic cells, possibly indicating an association between innate and systemic immunity." (PMID 37365284, 2023). "An obvious DDRi partner for a long-acting TOP1i would a PARPi, and the BRCA1-deficient MX-1 tumor used here is highly sensitive to both drugs." (PMID 37377899, 2023). "Genomic instability caused by BRCA1/2 deficiency leads to a higher neoantigen load and tumor mutational burden (TMB), which constitute an immune activation signature with a higher level of tumor infiltrating lymphocytes (TILs)." (PMID 37444415, 2023). "The sixth patient revealed comparable levels of BRCA1 methylation of both rs799905 alleles in blood (with a slight preference for methylation on the alternative allele), while the tumor carried methylation of the reference allele." (PMID 38053165, 2023). "The tumor is considered HRD-positive if a BRCA1/2 mutation is identified and/or the GI score is ≥42." (PMID 38067228, 2023). "Tumor characterization by HRD score testing identifies possible gene mutations (at the level of the BRCA1 and BRCA2 genes in the tumor tissue) and reveals genomic instability through LOH, LST, and TAI (collateral damage)." (PMID 37296748, 2023). "Tumor susceptibility gene BRCA1 is involved in transcriptional regulation, and its overexpression can increase the risk of BRCA." (PMID 36673982, 2023). "CTC (Circulating tumor cell) gene test was performed in peripheral blood, and the result showed BRCA1 gene mutation." (PMID 37234981, 2023).
tumor (continued). "The role of the vit-D3/VDR axis in the regulation of tumor angiogenesis was linked to the expression of the BRCA1 gene." (PMID 37835527, 2023). "Circulating tumour DNA analysis from the phase 2 TRITON2 trial demonstrated the prevalence of reversion mutations in BRCA1 or BRCA2 after progression on rucaparib." (PMID 37345149, 2023). "PARPi7 scores were higher in BRCA1 mutated, or methylated tumours compared with BRCA1/2 wild-type tumours (P < 0.001) and in HRD-high compared with low tumors (P < 0.001), this remained true in BRCA1/2 wild-type patients." (PMID 37574209, 2023). "PI3K inhibition is particularly useful in combination with PARP inhibition because it downregulates BRCA1/2, creating a BRCA-mutant-like tumor state and sensitizing BRCA1/2-proficient tumors to PARP inhibition." (PMID 36999995, 2023). "In a previous gene mutation analysis conducted in tumor tissue alone, more than 80% of BRCA1 and BRCA2 variants detected were reported to be of germline origin." (PMID 36494460, 2023). "Instead, samples of the two patients carrying germline variants of uncertain significance in BRCA1 displayed the loss of the allele harboring the variant in the tumor, due to allele deletion (GECO 2) or to CN-LOH (GECO 27)." (PMID 36900320, 2023). "While there are yet no studies determining the oncogenic drive of simultaneous mutations in BRCA1/2 and HER2, there are likely tumours that either show combined BRCA1/2 and HER2 mutation, or HER2 amplification with an intact BRCA1/2 pathway." (PMID 36831687, 2023). "All patients with a BRCA1/2 pathogenic variant detected in tumour DNA underwent germline BRCA1/2 testing." (PMID 38201604, 2023). "Between 11 April 2021 and 11 October 2023, 382 patients were successfully tested for tumour BRCA1 and BRCA2 variants." (PMID 38201604, 2023). "BRCA1-deficient tumor cells are sensitive to inhibitors of poly (ADP-ribose) polymerase (PARP1) through the mechanism of synthetic lethality." (PMID 36551764, 2022). "Other important tumor-suppressing genes that, once mutated, result in the occurrence of breast cancer include BRCA1 and BRCA2." (PMID 36233156, 2022). "Several reports point out that type I IFN signaling and anti-tumor immunity were induced by BRCA1/2 deletion which causing DSB accumulation and elevated levels of GI." (PMID 36226174, 2022). "Even more recently, reflex tumor testing for BRCA1/2 mutations was done directly by the Department of Pathology, signalling patients be referred to medical genetics if they tested positive." (PMID 36547149, 2022). "The concept of tumor testing has been introduced as an attractive approach that can potentially identify both germline and somatic BRCA1/2 pathogenic variants." (PMID 35813356, 2022). "Mutations in the RING domain inactivate BRCA1 E3 ligase activity, which decreases the tumor-suppressor activities of BRCA1." (PMID 35626055, 2022). "That all twelve clones isolated from the relapsed PDX tumor showed the same profile of heterozygous methylation suggests that demethylation of one BRCA1 promoter allele occurred in all or a vast majority of the cells comprising the entire recurrent tumor." (PMID 35857626, 2022). "As expected from a Brca1 deficiency–associated neoplasia, PARP inhibitor olaparib treatment attenuated disease phenotypes." (PMID 36346676, 2022). "Tumours with BRCA1 mutations are defective in repairing DNA damage thorough the homologousre combination pathway." (PMID 35735060, 2022). "BRCAness is the presence of a defect in the homologous recombination repair of tumor cells mimicking the loss of BRCA1 or BRCA2, as well as germline mutations." (PMID 36613648, 2022). "Overall, these results demonstrated that in vivo pyridostatin has an inhibitory effect against BRCA1‐mutated patient xenograft tumours that developed PARPi resistance." (PMID 35107878, 2022).
tumor (continued). "This translational research investigated the clinical significance of the immune microenvironment of TNBC in association with HRD, tumor BRCA1/2 (tBRCA1/2) mutation, and response to NAC." (PMID 35462552, 2022). "Targeted therapies against BRCA1/2‐mutated tumours exploit this vulnerability by introducing additional DNA lesions." (PMID 35107878, 2022). "CX-5461 was found to be synthetically lethal in BRCA2 and BRCA1-deficient tumor models both in vitro and in vivo, independently of RNA polymerase 1 inhibition." (PMID 35750695, 2022). "Subsequently, considering the germline BRCA1 pathogenic variant, she received third-line gemcitabine and cisplatin chemotherapy, but the tumor progressed after four cycles of treatment." (PMID 36463295, 2022). "Pyridostatin and its combinations with NU‐7441 and/or paclitaxel, specifically eliminate BRCA1/2‐deficient tumours in vivo." (PMID 35107878, 2022). "The current understanding of PARPi resistance is mainly focused on tumor cell-intrinsic mechanisms, including the cellular availability of PARPi, reversion mutations in BRCA1/2, restoration of HR or PARylation, and DNA replication fork protection." (PMID 35641483, 2022). "Damage that occurs to BRCA1 by chance prevents the protein from DNA repair process and thereby increases the risk of developing tumor." (PMID 34643844, 2022). "Here, the authors use highly multiplexed imaging to analyse the HGSOC immune microenvironment at spatial and single-cell resolution, with clinically relevant findings for BRCA1/2-mutated tumours." (PMID 35149709, 2022). "Consistent with this, we find that targeting C‐NHEJ with DNA‐PKcs inhibitors enhanced the efficacy of pyridostatin treatment against BRCA1/2‐deficient tumours, thus the two compounds act synergistically in this context." (PMID 35107878, 2022). "For TNBC patients who have BRCA defection or mutation, PARP inhibitors can block BRCA1/2-mediated homologous-recombinant based DNA double-strand break repair and promote tumor cell apoptosis." (PMID 35402236, 2022). "It was subsequently shown that the ability to eliminate BRCA1/2‐deficient cells and tumours is also a feature of the G4 ligand CX‐5461, which is currently evaluated in clinical trials in patients with DNA repair defects (NCT02719977 ClinicalTrials.gov)." (PMID 35107878, 2022). "To test if Tgfβr2 activation promotes EMT in Brca1 deficient tumor cells, we used a TGFβ challenge assay." (PMID 35236825, 2022). "In unselected TNBC patients, ~10% of the patients harbor a deleterious BRCA1/2 mutation, which results in tumours that are deficient in homologous recombination." (PMID 35124703, 2022). "The most common mechanisms of PARPi sensitivity of a BRCA1/2-deficient tumor are through synthetic lethality and PARP trapping, but others include the enhancement of c-NHEJ and the inhibition of alternative NHEJ." (PMID 36183837, 2022). "For Patient 6, a BRCA1 mutation carrier, we evaluated one primary tumor and three recurrences of TNBC." (PMID 36344544, 2022). "For tumor cells with BRCA1/2- or HR- deficiency, PARP1 activity is important for preventing the spontaneous ssDNA breaks that results in accumulation of DSBs." (PMID 36284291, 2022). "In this study, the molecular profile of different BRCA-associated tumor types was assessed with regard to the classification and annotation of detected BRCA1/2 variants." (PMID 35251494, 2022). "With respect to tumor testing, 25 (66%) patients had a BRCA1 mutation and 13 (34%) patients had a BRCA2 mutation (34%)." (PMID 36143252, 2022). "There are reports that a marked increase in the needs for BRCA1 causes BRCAness tumor formation in normal BRCA1 carrier or in tissues other than in breast or ovary tissue." (PMID 35327946, 2022). "The positive association between lymph node involvement and tumor size appears to be stronger in BRCA2 mutation carriers than in BRCA1 mutation carriers." (PMID 35507134, 2022).
tumor (continued). "Among the 247,926 tumors, we identified reversion mutations in 75 tumor samples: 32 with BRCA1 and 43 with BRCA2 reversion mutations." (PMID 36557020, 2022). "Poly ADP ribose polymerase (PARP) inhibition of cells containing a defect in homologous recombination pathways (e.g., those with BRCA1/2 mutations) results in the death of target tumor cells while sparing normal cells." (PMID 35267660, 2022). "Although the roles of BRCA1, such as DNA damage repair and stalled fork stabilization, obviously contribute to tumor suppression, these ubiquitously important functions cannot explain tissue-specific tumorigenesis by BRCA1 mutations." (PMID 35327946, 2022). "It seems, therefore, that the most justifiable algorithm for detecting a germinal mutation in these patients is to start testing BRCA1/2 genes using the NGS method in DNA extracted from tumour cells." (PMID 35382848, 2022). "Here, we demonstrate that pyridostatin exhibits a high specific activity against BRCA1/2‐deficient tumours, including patient‐derived xenograft tumours that have acquired PARP inhibitor (PARPi) resistance." (PMID 35107878, 2022). "This study only detected BRCA1/2 reversion mutations in tumour samples of 31.3% (5 of 16) patients in the second cohort with recurrent disease, among which 18.8% (3 of 5 patients) also had detectable reversions in cfDNA." (PMID 35545786, 2022). "In our study, we not only confirmed that the BRCA1 germline variants were still present in the tumor (with evidence of positive selection in case 1), but we also demonstrate scars of HRD in the three tumors." (PMID 35280729, 2022). "BRCA1/2 tumor mutations were present in 10% of cases, which is below the 20% of germline and somatic cases reported in HGS ovarian carcinoma." (PMID 35205662, 2022). "The possibility of newly arising BRCA1/2 mutations at recurrent disease can be excluded in our study cohort, as all patients where recurrent tumor was tested had germline mutations." (PMID 36143252, 2022). "In a PDX model, it has been demonstrated that NVB in combination with BRCA1-and-53BP1 loss of function reduces tumor growth." (PMID 35326571, 2022). "An important consequence of VEGFR inhibition is tumor hypoxia, a state that has been linked to HR defects via the downregulation of BRCA1, BRCA2, and RAD51." (PMID 35681619, 2022). "On the other hand, all of the cisplatin-treated tumor derived clones (12/12) showed both methylated and unmethylated signals, suggesting heterozygous loss of BRCA1 methylation at the cellular level." (PMID 35857626, 2022). "Herein, we aimed to shed more light into how BRCA1/2 mutations and single-cell tumor phenotypes shape the immune microenvironment and prognosis in HGSC." (PMID 35149709, 2022). "The nuclear location of BRCA1 has been linked to its tumor suppressor action, as it participates in DNA damage repair, cell cycle checkpoint control, and apoptosis signaling pathways." (PMID 36192752, 2022). "We aimed to discover how BRCA1/2 mutations shape the cellular phenotypes and spatial interactions of the tumor microenvironment." (PMID 35149709, 2022). "BRCA1 (BRCA1 DNA repair associated) is known as a cytoplasm–nuclear shuttling protein, and many tumor-associated mutations have altered the subcellular localization of BRCA1 protein." (PMID 35211510, 2022). "Most primary/recurrent tumor pairs had concordant BRCA1/2 allele-specific LOH status (20/27 patients; 74%)." (PMID 36344544, 2022). "BRCA1-reconstituted tumor cells have been found to be more sensitive to HDAC inhibitor-induced stem loss than BRCA1-deficient cells." (PMID 35870078, 2022). "Mutations of histone acetyltransferase EP300 are linked to a hyperacetylated state and tumor sensitivity to radiation therapy, through acetylation of BRCA1 promoter-associated histone 3 at lysine 27 (H3K27) and repression of homologous recombination repair." (PMID 35323317, 2022).